SLC7A5P1 (solute carrier family 7 member 5 pseudogene 1)
Synonyms: MLAS; LAT1-3TM; DC49; hLAT1-3TM
Gene: Transcribed unprocessed pseudogene on chromosome 16 (29,613,103 to 29,613,640, reverse strand). Ensembl gene ENSG00000260727.
Subcellular location: Membrane
Diseases named in the same sentence as SLC7A5P1 in open-access papers:
SLC7A5P1 is named in the same sentence as 1 disease in open-access papers, as found by Europe PMC text mining. Sharing a sentence is not in itself a finding about the gene and the disease. The quoted sentences say what the papers report.
epilepsy (1 paper, 2013). A brain disorder characterized by episodes of abnormally increased neuronal discharge resulting in transient episodes of sensory or motor neurological dysfunction, or psychic dysfunction. "Because of this technical artifact, more subjects with epilepsy were calculated to have deletions of SLC7A5P1 than those subjects with non-neurologic indications." (PMID 24086149, 2013).